MTCP1 (mature T cell proliferation 1)
Description:
Enhances the phosphorylation and activation of AKT1 and AKT2.
Synonyms: p13MTCP1; p8MTCP1; TCL1C
Tractability: Antibody: the Human Protein Atlas places it where antibodies can reach.
Gene: Protein-coding gene on chromosome X (155,064,034 to 155,147,937, reverse strand). Ensembl gene ENSG00000214827.
Subcellular location (Human Protein Atlas): Nucleoplasm; Plasma membrane
Gene Ontology:
Molecular function: protein kinase binding; protein serine/threonine kinase activator activity
Biological process: intracellular signal transduction
Homologues: Orthologues: chimpanzee MTCP1 (100% identical), macaque MTCP1 (100% identical), pig MTCP1 (99% identical), rabbit MTCP1 (99% identical), dog MTCP1 (98% identical), guinea pig MTCP1 (98% identical), mouse Mtcp1 (94% identical), rat Cmc4 (70% identical). Paralogues in human: TCL1A (37% identical), TCL1B (36% identical).
Diseases named in the same sentence as MTCP1 in open-access papers:
MTCP1 is named in the same sentence as 22 diseases in open-access papers, as found by Europe PMC text mining. Sharing a sentence is not in itself a finding about the gene and the disease. The quoted sentences say what the papers report.
leukemia (5 papers, 2008 to 2023). A malignant (clonal) hematologic disorder, involving hematopoietic stem cells and characterized by the presence of primitive or atypical myeloid or lymphoid cells in the bone marrow and the blood. "Further interrogating this phenomenon we demonstrate the capacity for MTCP1 to initiate development of an aggressive murine CLL-like leukemia, revealing MTCP1 as a target for exploring the pathogenic mechanisms driving CLL." (PMID 34732719, 2021). "Using detection of >20% CLL-like cells in the blood as a threshold for leukemia onset, Eμ-MTCP1 founder lines Z36 and Z20 reached “diseased” status at a median time of 7.7 and 16.7 months, respectively." (PMID 34732719, 2021). "A cohort of Eμ-TCL1 mice in our laboratory maintained a similar median time to CLL-like leukemia onset with Eμ-MTCP1 founder line Z36 and a similar median survival with Eμ-MTCP1 founder line Z20." (PMID 34732719, 2021). "AKT1 and AKT2 both interact with all TCL1 family members like TCL1, MTCP1, and TCL1b in leukemia cells and as consequence the activity of both isoforms is increased in an unspecific manner." (PMID 31752925, 2019). "While mechanisms supporting the observed variance in leukemia onset between Z20 and Z36 founder lines remain unresolved, insertion of the MTCP1 transgene in proximity to additional active enhancer regions or inaccessible in regions of condensed chromatin may be contributing to this distinction." (PMID 34732719, 2021). "Indeed, here we report overexpression of human MTCP1 restricted to the B cell compartment in mice produces a clonal CD5+/CD19+ leukemia recapitulating the major characteristics of human CLL and demonstrates favorable response to therapeutic intervention with ibrutinib." (PMID 34732719, 2021). "In addition, the over-expression of CMC4 (also known as MTCP1), as a favorable prognosis gene in our model, was discordantly reported to produce clonal CD5+/CD19+ leukemia in mice, which was thought to be a chronic lymphocytic leukemia driving gene." (PMID 36816541, 2023).
Moyamoya disease (3 papers, 2015 to 2021). Moyamoya disease (MMD) is a rare intracranial arteriopathy involving progressive stenosis of the cerebral vasculature located at the base of the brain causing transient ischemic attacks or strokes. "Case: We report the case of an adolescent male presenting with progressive and symptomatic moyamoya angiopathy and severe dilated cardiomyopathy caused by a hemizygous deletion of BRCC3/MTCP1." (PMID 33868155, 2021). "The critical region of overlap for syndromic moyamoya disease among these three families encompasses exon 1 of CMC4 and MTCP1 and the first three exons of BRCC3." (PMID 33193636, 2020). "Deletions including FUNDC2, CMC4, MTCP1, and BRCC3 were reported in individuals with syndromic Moyamoya disease, characterized by angiopathy, short stature, and distinctive facial features." (PMID 25927380, 2015). "Recently, an ~150 kb deletion of Xq28 encompassing part of F8, FUNDC2, CMC4, MTCP1, and BRCC3 was reported in a child with severe hemophilia A, Moyamoya disease, and distinctive facial features." (PMID 25927380, 2015).
chronic lymphocytic leukemia (2 papers, 2021 to 2023). "Here, the authors report a translocation involving MTCP1 in chronic lymphocytic leukemia and show that MTCP1 overexpression leads to the disease in a murine model." (PMID 34732719, 2021).
Splenomegaly (2 papers, 2021 to 2024). Abnormal increased size of the spleen. "Eμ-MTCP1 mice meeting ERC due to CLL-like disease invariably presented with splenomegaly accompanied by abdominal lymphadenopathy." (PMID 34732719, 2021).
lymphoma (1 paper, 2021). A malignant (clonal) proliferation of B- lymphocytes or T- lymphocytes which involves the lymph nodes, bone marrow and/or extranodal sites. "To date, MTCP1 on the Xq28 locus has not been implicated in B-cell leukemia or lymphoma." (PMID 34732719, 2021).
mantle cell lymphoma (1 paper, 2025). Mantle cell lymphoma is a rare form of malignant non-Hodgkin lymphoma affecting B lymphocytes in the lymph nodes in a region called the ``mantle zone''. "Examples include TRA::MTCP1 for T-PLL, TYK2 rearrangement for T-cell lymphomas; CCND1 and CCND2 rearrangement with IGK and IGL in mantle cell lymphoma; MYC rearrangements and hyperdiploidy in multiple myeloma." (PMID 40361363, 2025).
T-cell leukemia (1 paper, 2025). A malignant disease of the T-lymphocytes in the bone marrow, thymus, and/or blood. "The pathogenesis of T-PLL involves rearrangement of the TCR, located on chromosome 14q) and juxtaposition with T-cell leukemia (TCL) genes, leading to the aberrant expression of TCL1A, TCL1B, or MTCP1 oncogenes in approximately 95% of cases." (PMID 41259500, 2025).
cancer (3 papers, 2017 to 2021). A tumor composed of atypical neoplastic, often pleomorphic cells that invade other tissues. "We reinforce the importance of genetic interrogation of rare, recurrent balanced translocations to identify cancer driving genes via the story of MTCP1 as a contributor to CLL pathogenesis." (PMID 34732719, 2021). "Interacting genes included well-established cancer-connected genes such as DNMT3A, SMAD2, MTCP1 and TLE4 (refs 36, 37, 38, 39)." (PMID 28534499, 2017). "Still inside the X-chromosome cluster, there are a few cancer-related genes (ATRX, MTCP1, PHF6), but the majority of the genes should be just the results of the X-chromosome inactivation." (PMID 28198667, 2017).
tumor (3 papers, 2020 to 2024). "Although the overall transcriptome profile remained largely similar between Eμ-MTCP1 and Eμ-TCL1 tumor cells, further investigation to define the significance in variation between MTCP1- and TCL1-driven CLL is warranted." (PMID 34732719, 2021). "One recent study using the nude mouse tumor model showed that suppression of CMC4 (misnamed as MTCP1 in this study, since the antibody used is for the peptide encoded by CMC4) by miR-126 is involved in repression of tumor growth and migration." (PMID 33193636, 2020). "Additional amplification of WT1, ERC1, ASIC2 and MTCP1 and deletion of CDKN2A and MLLT3 were found in recurring MFS (case 8b) but not in the original tumor (case 8a)." (PMID 38791144, 2024).
MTCP1 also shares sentences with these, for which no sentence is quoted: hemophilia A (2 papers); acute myeloid leukemia (1); cataract (1); clear cell renal carcinoma (1); dilated cardiomyopathy (1); Duodenal stenosis (1); Gynecomastia (1); hemophilia (1); infection (1); Klinefelter syndrome (1); multiple myeloma (1); prolymphocytic leukemia (1); T-cell lymphomas (1).